LRRK2 (leucine rich repeat kinase 2)
Diseases named in the same sentence as LRRK2 in open-access papers (continued):
Sharing a sentence is not in itself a finding about the gene and the disease.
atherosclerosis (2 papers, 2011 to 2013). A disease characterized by the build-up of fatty material and calcium deposition in the arterial wall resulting in partial or complete occlusion of the arterial lumen. "Interestingly, increased presence of CD14+CD16+ cells is commonly associated with inflammatory diseases such as Atherosclerosis, Kawasaki disease or bacterial infection and LRRK2 participates to antibacterial responses." (PMID 21738687, 2011). "For example, the elevated cholesterol observed in the LRRK2 KO rats is not a good model of human cholesterol related diseases such as atherosclerosis since rat serum cholesterol is primarily composed of high density lipoproteins." (PMID 24244710, 2013).
Bradykinesia (2 papers, 2024 to 2025). Bradykinesia literally means slow movement, and is used clinically to denote a slowness in the execution of movement (in contrast to hypokinesia, which is used to refer to slowness in the initiation of movement). "This discrepancy may be attributed to differences in experimental animals (i.e., rats and flies; cocaine-induced behavioral sensitization and LRRK2-G2019S-induced bradykinesia)." (PMID 39669198, 2024).
Chronic colitis (2 papers, 2024 to 2025). A chronic inflammatory disease of the large intestine (colon, cecum and rectum). "Previous models of mild chronic colitis using dextran sodium sulphate (DSS) induced more severe motor dysfunction, microglia activation, and dopaminergic neuron loss in genetic models of PD such as mice carrying the LRRK2 G2019S variant." (PMID 41103722, 2025).
ciliopathies (2 papers, 2018 to 2022). "Finally, it is important to note that LRRK2-mediated familial Parkinson’s disease is quite distinct from more classic diseases of ciliogenesis called ciliopathies." (PMID 30398148, 2018).
demyelinating disease (2 papers, 2024). A broad group of disorders that affect the myelin sheaths that cover the neurons. "Therefore, the inhibition of LRRK2 may synergistically trigger beneficial anti‐inflammatory and (re)myelination pathways with potential high impact in MS and other demyelinating diseases." (PMID 38287523, 2024).
erectile dysfunction (2 papers, 2008 to 2025). Persistent or recurrent inability to achieve or to maintain an erection during sexual activity. "11% of men with LRRK2 Gly2019Ser reported erectile dysfunction, all of whom were older than 60 years." (PMID 18539534, 2008).
Gastrointestinal dysmotility (2 papers, 2019). Abnormal intestinal contractions, such as spasms and intestinal paralysis, related to the loss of the ability of the gut to coordinate muscular activity because of endogenous or exogenous causes. "Leucine-rich repeat kinase 2 is associated with activation of the paraventricular nucleus of the hypothalamus and stress-related gastrointestinal dysmotility." (PMID 31827437, 2019). "Our study has highlighted LRRK2 as a new candidate molecule regulating PVN reactivity in stress and gastrointestinal dysmotility." (PMID 31555076, 2019). "Taken together, our present findings suggest that LRRK2 is a newly recognized molecule regulating the stress pathway in the PVN, thus playing a role in stress-related gastrointestinal dysmotility." (PMID 31555076, 2019).
glioblastoma (2 papers, 2011 to 2015). The most malignant astrocytic tumor (WHO grade IV). "Activation of ERK by the transformation of human mesenchymal stem cells by H-ras, overexpression of TrkA (tropomyosin-related kinase A) in glioblastoma cells and overexpression of mutant LRRK2 (leucine rich repeat kinase 2) in neuronal cells was associated with increase in autophagy." (PMID 24212825, 2011).
intestinal infection (2 papers, 2018 to 2025). "In the present study, we have systematically investigated the early immune response to intestinal infection in the context of PD-associated LRRK2 G2019S." (PMID 40883285, 2025). "Here, we sought to systematically investigate the effects of the PD causal Lrrk2 G2019S mutation in the mouse endogenous genome (G2019S knock-in mice) at steady state and in the early response to intestinal infection." (PMID 40883285, 2025). "Another report from Zhang and colleagues described the enhanced susceptibility of Lrrk2 KO mice to intestinal infection, and suggested a possible role of LRRK2 in maintaining symbiosis with commensal bacteria to control intestinal infection." (PMID 32714591, 2018). "Together, these results point to a role for LRRK2 in immune cells during the earliest responses following intestinal infection." (PMID 40883285, 2025).
lymphoma (2 papers, 2022 to 2025). A malignant (clonal) proliferation of B- lymphocytes or T- lymphocytes which involves the lymph nodes, bone marrow and/or extranodal sites. "Genetic silencing demonstrated that LRRK2 sustains the proliferation of lymphoma cells, a finding paired with the association between high expression levels and inferior outcome in DLBCL patients." (PMID 36051080, 2022). "Our results represent the very first evidence for a possible role of LRRK2 in lymphomas, and for the inhibition of its kinase activity as potential therapeutic approach." (PMID 36051080, 2022). "Given that very little is known about LRRK2 in lymphomas, we looked at its expression pattern in DLBCL, taking advantage of two available datasets (phs001444.v2.p1, EGAD00001003140)." (PMID 36051080, 2022). "In conclusion, we have identified a series of combinations that can improve the response to BET inhibitors in lymphomas, and we have identified LRRK2 as a gene essential for lymphomas and as a putative novel target for the development of antilymphoma agents." (PMID 36051080, 2022). "The addition of LRRK2‐IN‐1 was synergistic with birabresib in all the six lymphoma cell lines, increasing apoptosis after BET inhibition, and the effect was in vivo validated using a GCB DLBCL xenograft." (PMID 36051080, 2022). "We identified combinations that can improve the response to BET inhibitors in lymphomas, and LRRK2 as a gene essential for lymphomas and as putative novel target for this type of tumors." (PMID 36051080, 2022). "Importantly, our data also identified LRRK2 as a novel putative target for lymphoma treatment with a prognostic role in DLBCL patients." (PMID 36051080, 2022). "While the inhibition of the first targets had already been reported as synergistic with BET inhibitors in lymphomas, less or no data were available for the combination with JAK and LRRK2 inhibitors, respectively." (PMID 36051080, 2022).
metabolic syndrome (2 papers, 2020 to 2021). A cluster of metabolic risk factors for CARDIOVASCULAR DISEASES and TYPE 2 DIABETES MELLITUS. "These authors accomplished an interesting study wherein they analyzed the possible influence of the metabolic syndrome in GBA- and LRRK2-associated PD patients compared with sPD." (PMID 34272400, 2021).
non-small cell lung carcinoma (2 papers, 2019 to 2020). A group of at least three distinct histological types of lung cancer, including non-small cell squamous cell carcinoma, adenocarcinoma, and large cell carcinoma. "Using multigene testing panels, LRRK2 demonstrated a prognostic significance in different types of cancers, including oral squamous cell carcinomas, intrahepatic cholangiocarcinoma, non-small-cell lung cancer, and colon cancer." (PMID 32722212, 2020). "By querying the OncoKB database for genes located at 12q12, only ARID2 deletion was found to be likely oncogenic, specifically in non-small cell lung cancer and hepatocellular carcinoma; in our analysis, ARID2 whole gene deletion co-occurred in 14.53% of LRRK2 CNV-altered cases." (PMID 32722212, 2020).
osteoarthritis (2 papers, 2025 to 2026). A noninflammatory degenerative joint disease occurring chiefly in older persons, characterized by degeneration of the articular cartilage, hypertrophy of bone at the margins and changes in the synovial membrane. "The engineered exosomes were loaded with a small inhibitor, LRRK2-IN-1, which inhibited osteoarthritis-related inflammation and immune-related gene expression." (PMID 41294599, 2025).
osteoporosis (2 papers, 2017 to 2021). A condition of reduced bone mass, with decreased cortical thickness and a decrease in the number and size of the trabeculae of cancellous bone (but normal chemical composition), resulting in increased fracture incidence. "Candidate osteoporosis genes commonly shared with AD and PD may include the LRP5 and LRP6 genes, which are partially affected by LRRK2 mutations, in the canonical Wnt signaling pathway." (PMID 34955816, 2021).
papillary renal cell carcinoma (2 papers, 2015 to 2020). A rare subtype of renal cell carcinoma, arising from the renal tubular epithelium and showing a papillary growth pattern, which typically manifests with hematuria, flank pain, palpable abdominal mass or nonspecific symptoms, such as fatigue, weight loss or fever. "A biostatistics and microarray survey in PTC and papillary renal cell carcinomas detected concomitant overxpression of LRRK2 and the MET proto-oncogene." (PMID 25923053, 2015).
papillary thyroid carcinoma (2 papers, 2020 to 2024). "Silencing of lncRNA RP11-476D10.1 expression enhances apoptosis and autophagy in papillary thyroid carcinoma cells; lncRNA RP11-476D10.1 binds to miR-138-5p and promotes leucine-rich repeat kinase 2 (LRRK2) expression." (PMID 38481525, 2024).
prediabetes (2 papers, 2020 to 2025). "LRRK2-PD had higher levels of triglycerides (p = 0.015) and higher rates of prediabetes (p = 0.004), while LRRK2-NMC had higher triglyceride levels (p = 0.014)." (PMID 32518334, 2020). "Supporting our hypothesis are data derived from LRRK2 variant carriers, who have a higher prevalence of prediabetes and elevated triglyceride levels compared to non-carriers and individuals with PD due to other genetic mutations." (PMID 40676250, 2025). "LRRK2-PD had higher UPSIT scores (p = 0.008), higher rates of prediabetes (p = 0.004) and higher triglyceride levels (p = 0.015) which were correlated with disease duration (r = 0.332, p = 0.036) and LEDD (r = 0.432, p < 0.001)." (PMID 32518334, 2020). "LRRK2-PD had higher rates of prediabetes compared with both iPD and GBA-PD with no clinical impediment." (PMID 32518334, 2020). "While elevated triglycerides and prediabetes were more frequent among LRRK2 carriers, MS does not seem to influence GBA and LRRK2-PD phenotype." (PMID 32518334, 2020).
prostate carcinoma (2 papers, 2021 to 2025). A carcinoma that arises from epithelial cells of the prostate gland. "Some papers suggest an association between LRRK2 and hormone-related cancers, such as breast and prostate cancer." (PMID 40660132, 2025). "Our findings suggest that specific genetic mutations, including PIK3CA, LRP6, LRRK2, and BRCA2, are linked to prostate cancer metastasis and BCR." (PMID 40660132, 2025). "Our study identified mutations in LRRK2 and LRP6 in 7.5% and 2.8% of all prostate cancer patients, respectively, with the majority observed in cases of metastatic prostate cancer." (PMID 40660132, 2025). "We identified “Prostate Cancer”, “MTOR signaling pathway”, “RIG-I-like receptor signaling pathway”, “ERBB signaling pathway”, “JAK-STAT signaling pathway” and “Apoptosis” as the potential functional enriched pathways modulated by LRRK2." (PMID 34217264, 2021).
renal cell carcinoma (2 papers, 2021). "The epidermal growth factor receptor (EGFR) signaling pathway plays a critical role in the pathogenesis and progression of renal cell carcinoma, suggested that LRRK2 may play an important role in ccRCC as well." (PMID 34217264, 2021). "We speculate that LRRK2 can be a novel prognostic biomarker of renal cell carcinoma." (PMID 34217264, 2021).
Sepsis (2 papers, 2024 to 2025). Sepsis is defined as life-threatening organ dysfunction caused by a dysregulated host response to infection. "In the present study, several genes associated with ER stress, including XBP1, HERPUD1, LRRK2, and SELENOS, were downregulated in foals suffering from sepsis, showing a negative correlation with the sepsis score." (PMID 40867920, 2025). "Surprisingly, 72-hours post sepsis, serum LRRK2 levels only modestly increase in female mice, and not at all in male mice." (PMID 38862989, 2024). "For example, a diminished level of total Rab10 in serum, such as through immune cell depletion or that we observed in sepsis, may not necessarily reflect diminished LRRK2 activity should the ratio of pT73-Rab10 to total Rab10 persist at normal levels." (PMID 38862989, 2024). "In contrast, XBP1 (p = 0.002), HERPUD1 (p = 0.002), LRRK2 (p = 0.015), and SELENOS (p = 0.008) showed a significant negative correlation with sepsis score." (PMID 40867920, 2025). "Conversely, XBP1, HERPUD1, LRRK2, and SELENOS exhibited a negative correlation with sepsis scores and a positive correlation with the combined activities of antioxidant enzymes, highlighting the potential of ER stress as a novel therapeutic target and prognostic marker in septic foals." (PMID 40867920, 2025).
Splenomegaly (2 papers, 2011 to 2020). Abnormal increased size of the spleen. "WT and Lrrk2-deficient mice were infected with Salmonella enterica serovar Typhimurium, and three markers of inflammation were measured: IL-18, IFN-γ, and splenomegaly." (PMID 32111741, 2020). "For example, LRRK2 KO mice have a tendency to develop splenomegaly." (PMID 21738687, 2011).
steatosis (2 papers, 2020 to 2024). Increased lipid within the cytoplasm of cells. "The steatosis in the livers and kidneys in LRRK2 knockout mice may be as a result of the diminished β-oxidation regulated by LRRK2." (PMID 32916992, 2020). "The transmission electron microscopy revealed edema and steatosis of variable degrees in liver cells from the TAA-intervened mice, with the most serious hepatocytic necrosis in the Lrrk2−/−-HE mice." (PMID 38725082, 2024).
acute pancreatitis (1 paper, 2024). An acute inflammatory process that leads to necrosis of the pancreatic parenchyma. "In this Minireview article, we discuss how activation of LRRK2 by the recognition of fungi induces severe acute pancreatitis." (PMID 38440723, 2024). "In contrast, compared with LRRK2-intact mice, LRRK2-TG mice exhibited a more severe form of acute pancreatitis characterized by elevated levels of amylase, pancreatic accumulation of immune cells, and destruction of the pancreatic acinar architecture." (PMID 38440723, 2024).
adenoma (1 paper, 2024). A neoplasm arising from the epithelium. "Approximately 30.6% of the polyps developed in WT mice were small adenomas (2–5 mm diameter), in contrast with 45% in LRRK2 KI mice." (PMID 38607004, 2024).
Akinesia (1 paper, 2017). Inability to initiate changes in activity or movement and to perform ordinary volitional movements rapidly and easily. "These experiments show that the expression of high kinase forms of LRRK2 reduces the proportion flies showing PER, i.e. they show akinesia." (PMID 29214211, 2017).
alcohol abuse (1 paper, 2021). The use of alcoholic beverages to excess, either on individual occasions ("binge drinking") or as a regular practice. "The analysis of LRRK2 variants was extended to a second replication cohort, composed of 1,316 North Americans [National Institutes of Health–National Institute on Alcohol Abuse and Alcoholism (NIH-NIAAA)]." (PMID 34135785, 2021).
alcohol dependence (1 paper, 2021). Physical and psychological dependence on alcohol. "Taken together, these results support the notion that LRRK2 variants are risk factors for alcohol dependence in humans." (PMID 34135785, 2021). "In conclusion, this study demonstrated, for the first time, the association of LRRK2 variants with alcohol dependence in three different human populations." (PMID 34135785, 2021). "In the present study, we first identified four variants (rs4768231, rs4767971, rs7307310, and rs1465527) in the LRRK2 gene that were associated with alcohol dependence in a cohort from Brazil (Bambuí)." (PMID 34135785, 2021). "Further studies are required to evaluate the role of the variants associated with alcohol dependence in LRRK2 expression." (PMID 34135785, 2021). "Considering the convergent results found for the LRRK2 gene from animal models and human brain, we hypothesized that LRRK2 variants could represent genetic risk factors for alcohol dependence in humans." (PMID 34135785, 2021). "Interestingly, the LRRK2 variants were associated with alcohol dependence only in individuals with European AIM score below the median in the US cohort." (PMID 34135785, 2021). "Markers in the LRRK2 locus associated with alcohol dependence in humans." (PMID 34135785, 2021). "Importantly, the LRRK2 alleles associated with a high risk of alcohol dependence were the same in the cohorts from Brazil and the United States." (PMID 34135785, 2021). "In the present study, we investigate the association of LRRK2 variants and alcohol dependence in three distinct multiethnic cohorts, two from Brazil and one from the United States, and consistently show that intronic single-nucleotide polymorphisms (SNPs) were associated with alcohol dependence." (PMID 34135785, 2021). "Specifically, no genetic variation in LRRK2 has been found to reach genome-wide significance level in recently published and well-powered genome-wide association studies (GWASs) on alcohol dependence." (PMID 34135785, 2021).
Apathy (1 paper, 2023). Apathy is a quantitative reduction of interest, motivation and the initiation and persistence of goal-directed behavior, where often the accompanying emotions, thoughts, and social interactions are also diminished. "The patient carrying PRKN deletion of exon 4, LRRK2 deletion of exon 49, and MAPT p.Asn596Lys had dominant motor disturbances (high MDS‐UPDRS score of part III), but without the presence of apathy as previously reported." (PMID 36879366, 2023).
Atrophy (1 paper, 2024). Any weakening or degeneration, especially through lack of use. "The results in the asymptomatic LRRK2 cases with poorer cognitive outcome in people with a younger brain age give rise to the hypothesis that the brain-age algorithm here does not detect an effect of atrophy but possibly reactive effects to preclinical accumulation of pathology." (PMID 39713239, 2024).
cavernous hemangioma (1 paper, 2016). A hemangioma characterized by the presence of cavernous vascular spaces. "While surveying a LRRK2 knockout mouse strain, we found that old animals developed age-dependent hepatic vascular growths similar to cavernous hemangiomas." (PMID 27872856, 2016).
cocaine abuse (1 paper, 2019). Disorders related or resulting from use of cocaine. "As SNCA is one of the most common cause of PD there are possibility that other genetic risk factors, such as PARK2, LRRK2, PINK1 and DJ-1, also could contribute to the development of PD even in early age due to the cumulated effect of cocaine abuse and genetic risk." (PMID 31660902, 2019).
coronary artery disease (1 paper, 2025). "Genes associated with PD, including α‐synuclein, Parkin, PINK1, DJ‐1, and LRRK2, may contribute to the connection between PD and coronary artery disease (CAD)." (PMID 39817587, 2025).
diabetic nephropathy (1 paper, 2022). "We assessed whether long-term LRRK2 inhibition by GNE-7915 caused renal effects, including changes in kidney gross morphology, serum creatinine levels, and urinary ACR (a marker of early renal diseases or diabetic nephropathy)." (PMID 36088364, 2022).
dominant Parkinson's disease (1 paper, 2015). "Mutations in the gene encoding leucine-rich repeat kinase 2 (LRRK2) are related to autosomal dominant Parkinson's disease form." (PMID 26064418, 2015).
female infertility (1 paper, 2014). Diminished or absent ability of a female to achieve conception. "Expression of lrrkGS, which is analogous to the most common PD-causing mutation in human LRRK2 (G2019S), also suppressed female infertility in lrrk NS flies." (PMID 25288684, 2014).